IL6 (interleukin 6)
Diseases named in the same sentence as IL6 in open-access papers (continued):
Sharing a sentence is not in itself a finding about the gene and the disease.
COVID-19 (continued). "While EBV viraemia correlated with COVID-19 patients’ serum IL-6 level, this was not the case in controls (p = 0.006)." (PMID 35729310, 2023). "The apparent lack of clear efficacy of IL-6 blocking on COVID-19 can be due to differences in patients’ subpopulations or to differences in trial design." (PMID 36791125, 2023). "However, HD patients with COVID-19 symptom worsening showed up-regulation (more than 2.5-fold increase) of GM-CSF, IFN-γ, IL-1β, IL-2, IL-6, IL-17A and IL-21, and down-regulation of TNF-α and IL-8 serum levels after the dialysis procedure." (PMID 36675231, 2023). "Compared with COVID-19 patients without myocardial injury, the levels of IL6 in patients with myocardial injury increased, while the number of CD4+ T cells, CD8+ T cells, B cells, and NK cells decreased (P<0.05)." (PMID 37564653, 2023). "The clinical symptoms of COVID-19 relate to several cytokines including interleukin (IL)-2, IL-7, IL-10, tumor necrosis factor (TNF) with IL-6, IL-6-signal transducer and activator of transcription 3 (STAT3) and nuclear factor kappa B (NF-κB) pathway being of high significance." (PMID 36987476, 2023). "The trends of IL6, CRP, and hs-TnI were analyzed in COVID-19 patients with myocardial injury." (PMID 37564653, 2023). "Cytokines/chemokines (IL-6, CXCL-10 (IP-10), HGF, MIG, MCP-1, and G-CSF) and lipid mediators (TxB2, 11-HETE, 9-HODE, 13-HODE, 5-HETE, 12-HETE, 15-HETE, 14S-HDHA, 17S-HDHA, and 5-oxo ETE) were significantly elevated in COVID-19 patients compared to controls." (PMID 37685858, 2023). "There were significant differences in neutrophil, lymphocyte, eosinophil (Eos), C-reactive protein (CRP), D-dimer, lactate dehydrogenase (LDH), glucose, IL-6, ferritin, CD4 + T cell, CD4+/CD8 + T cell, CD8 + T cell, and B cell counts in the serum of the four COVID-19 patient groups (P < 0.05)." (PMID 37705107, 2023). "As such, upregulation of IL-6 and TNF-α are core components of the cytokine storm in COVID-19." (PMID 36769623, 2023). "Studies published so far showed that IL-6 is a predictor of severity in COVID-19 patients without diabetes." (PMID 37834356, 2023). "Meta-regression (adjusted for age and COVID-19 severity) showed that being in the ICU (adjusted OR 3·69 [95% CI 1·27–10·68]), receiving IL-6 inhibitors (1·44 [1·03–2·01]), and having diabetes (1·95 [1·19–3·21]) were associated with increased odds of the presence of antibiotic-resistant isolates." (PMID 36736332, 2023). "Tocilizumab, an anti-IL-6 medication, and baricitinib, a JAK kinase inhibitor, are used in patients with rapidly progressing COVID-19.81,82 Despite the clinical improvement these drugs can provide, they also increase the risk of bacterial infection, including HAIs." (PMID 36601548, 2023). "Although iron parameters are not regarded as biomarkers predicting septic development and are not mentioned in the recommendations for the management of COVID-19 the relationship between IL-6 and iron metabolism is well recognized." (PMID 37896877, 2023). "Finally, monocytes from convalescent COVID-19 patients demonstrate significantly decreased TNF-α and IL-6 expression in response to LPS stimulation compared to control subjects." (PMID 38250080, 2023). "Hamster models infected with SARS-CoV-2 and patients who died from COVID-19 showed impaired BBB permeability, microglial activation, and increased brain expression of IL-1β and IL6 within the hippocampus and the inferior olivary nucleus of the medulla when compared to the control groups." (PMID 37686360, 2023). "The immune response in COVID-19, which may result in ARDS, involves the unbalanced secretion of various inflammatory cytokines and chemokines, including TNF-α, IL-1β, IFN-γ, IL-6, IL-10, IL–1RA, IP–10, MCP–1, and IL-8 (CXCL8)." (PMID 37600829, 2023). "Negative likelihood ratios indicate that IL-6, PCT, and CRP at hospital admission can be used for identifying patients at low risk for severe COVID-19 progression." (PMID 37937220, 2023).
COVID-19 (continued). "Another study performed on 149 COVID-19 patients found that treatment with another IL-6 antagonist sarilumab did not significantly affect D-dimer levels in hospitalized COVID-19 patients compared to placebo." (PMID 37046952, 2023). "The downregulation of the NF-κB/MAPK signaling pathway was postulated to decrease pro-inflammatory cytokines such as IL-6, TNF-α, IL-1β, CXCL10/IP-10, CCL2/MCP-1, and IL-8, suggesting that it may prevent cytokine storm in COVID-19." (PMID 37298539, 2023). "Patients diagnosed with COVID-19 had an extreme amount of mRNA generation and production of the cytokines IL-1β, IL-6, TNF-α, and IL-18; however, patients treated with nano curcumin exhibited a substantial decline in IL-6 and IL-1β levels." (PMID 37033493, 2023). "On the other hand, when PBMCs were stimulated with LPS, the relative production of IL-6 cytokines was lower in the post-COVID-19 group (ES = 0.75) and TNF-α was not different between the groups." (PMID 37753077, 2023). "In the first, for patients admitted to the general ward with lower severity scores than in our study, DXM that was administered within 19 h of collection reduced plasma IL-6 and IL-1ra levels but did not influence COVID-19 coagulation disorders." (PMID 37108440, 2023). "Enrichment of IL-20, IL-2, IL-6, KIT, and JAK-STAT signaling pathways was unique to monocytes and DCs from patients with COVID-19, suggesting that innate immune cells may be much more active and cytotoxic in COVID-19 compared to in HIV-1." (PMID 36992700, 2023). "A meta-analysis of the first published trials in patients with COVID-19 treated by anti-IL-6 agents showed no statistically significant reduction in intensive care unit transfer." (PMID 37298597, 2023). "Furthermore, IL-6 increases endothelial expression of adhesion molecules and molecules that regulate inflammatory cell migration, such as MCP-1, a feature of COVID-19." (PMID 37111341, 2023). "While IL-6 and ferritin are indicators of COVID-19 severity, they did not correlate with plasma IGFBP-2." (PMID 38137505, 2023). "Moreover, this cytokine storm also has an impact on the adaptive immune response, since the low expression of HLA-DR induced by high concentrations of IL-6 and TNF-α leads to a pronounced lymphopenia in severe COVID-19 cases." (PMID 37153606, 2023). "Some elevated cytokine levels, such as interleukin-6 (IL-6), tumor necrosis factor (TNF), interferons (IFNs), granulocyte-macrophage colony-stimulating factor (GM-CSF), and interleukin-18 (IL-18), are often reported in severe-critical patients with COVID-19." (PMID 36679421, 2023). "In this study, the circulating cytokines quantification showed that patients with COVID-19 have increased levels of IL-6 and IL-10 in the collections 4–6 days regardless of severity." (PMID 37515295, 2023). "The aim of this study was to investigate the relationship between the serum levels of a panel of pro-inflammatory cytokines consisting of IL-6, IL-8, IL-10, IL-12, TNF-α, IFN-γ and disease severity, need for oxygen therapy, ICU transfer and fatal outcome in patients with confirmed COVID-19." (PMID 37969879, 2023). "As a result, no single study influenced the significance of either the pooled estimate of IL-6 or the comparison of pooled IL-6 estimates for long COVID-19 patients and healthy individuals or those without PASC." (PMID 37095536, 2023). "These identified cytokines, such as IL-6, CXCL10, and CSF2, could be potential therapeutic targets for COVID-19 damage management." (PMID 38143441, 2023). "As reported by others, CRP, IL6, IL1β, but not TGFβ levels increased in patients with more severe stages of COVID-19." (PMID 38313435, 2023). "In COVID-19, CSS was found to be a common phenomenon, and IL-6 was a predominant cytokine." (PMID 37243203, 2023). "However, increases in IL-6, IL-8 and AT1R antibodies have also been observed in long COVID-19 and post-COVID-19 ME/CFS." (PMID 38005974, 2023).
COVID-19 (continued). "Therapies such as convalescent plasma, corticosteroids, IL-6 antagonists, and other anti-SARS-CoV-2 monoclonal antibodies are either approved or recommended to improve prognosis and reduce the clinical burden of COVID-19." (PMID 37021053, 2023). "The study showed an association between patients who did not receive corticosteroids and an increased expression of IL-6 (p = 0.049) within the COVID-19 group." (PMID 36992415, 2023). "Throughout the study there was no invasive and very limited non-invasive ventilatory support available for COVID-19 patients and no access to newer therapies such as interleukin-6 antagonists." (PMID 36750921, 2023). "Serum IL-6 levels and NLR are higher in severe COVID-19 than in mild COVID-19 cases." (PMID 38099004, 2023). "Furthermore, miR-29a-3p and -29b-3p depletion has shown to increase circulatory levels of IL-6, the direct activator of the IL-6/STAT3 axis, and in patients with COVID-19 these two miRs were found to be downregulated." (PMID 36834984, 2023). "In the present study, all COVID-19 patients exhibited significantly higher levels of IL-6, CXCL-10, HGF, MIG, MCP-1, and G-CSF than the non-COVID-19 respiratory disease controls." (PMID 37685858, 2023). "Interestingly, mounting evidence from clinical studies suggests that this PPAR agonist prevents the ARDS/ALI in COVID-19 patients by downregulating NF-κB and JAK/STAT signaling and then reducing TNF-α, IL1β, and IL6 levels." (PMID 36875108, 2023). "IL-6, TNFα, and IL-10 levels were highest in severe and critical COVID-19 patients, with comparable levels to non-COVID-19 critical patients." (PMID 36509969, 2023). "Significant negative correlations were observed between IL-6 with Ang II (Spearman r=-0.60, P = 0.0003), Ferritin with Ang II (Spearman r=-0.46, P = 0.004) among COVID-19 mild cases." (PMID 38057707, 2023). "Elevated IL-6, IL-18 and IL-8 levels have been also described in the serum and CSF of COVID-19 patients in parallel with elevated serum NfL, but not with CSF NfL." (PMID 36769057, 2023). "Another study reported higher serum levels of IL-6, IL-7, IL-10, granulocyte colony-stimulating factor (G-CSF), M-CSF, IP-10, monocyte chemoattractant protein-1 (MCP-1), MCP-3, MIG, and macrophage inflammatory protein 1α (MIP1α) is severe COVID-19 patients." (PMID 36825200, 2023). "Similarly, elevated levels of IL-6, IL-10, IL-2 and IFN-γ were found in patients with severe COVID-19 due to respiratory failure." (PMID 37917760, 2023). "Of those, IL-8, IL-6 and TNF-α were the most enhanced in HD + COVID-19 patients." (PMID 36675231, 2023). "Clinical data indicate that a hyperinflammatory response (an excessive release of pro-inflammatory cytokines e.g. interleukin 6 (IL-6) and IL-1b with secondary tissue damage) to SARS-CoV-2, contributes to disease severity and death in patients affected by COVID-19." (PMID 38034686, 2023). "Both IL-6 and CRP levels were increased in COVID-19 patients compared to healthy controls." (PMID 37051252, 2023). "The RS between activation marker concentrations and the severity of COVID-19 are calculated by training data set Z2KP, where the activation markers are IL-17a, IL-2, GATA3, IFN-γ, IL-4, IL-10, PD_1, CD40L, RORγt, CTLA_4, CCR7, TNF-α and IL-6, respectively." (PMID 36845115, 2023). "COVID-19/PLWH with a CD4 count ≤200 cells/μL could be distinguished from those with higher CD4 counts by lower levels of VEGF and higher levels of IL-6." (PMID 37646024, 2023). "The ongoing inflammatory response after acute COVID-19 remission keeps the expression of proinflammatory cytokines such as IFN-β, IFN-λ1, IFN-γ, IL-2, IL-6, IL-17, CXCL8, CXCL9, and CXC10 upregulated, the activation of non-classical and intermediate monocytes, fibroblasts, and myeloid cells." (PMID 38097988, 2023). "The median (minimum-maximum) IL-6 levels in COVID-19 non-survived group was 99.66 pg/ml (77.89–252.58) which was higher than the survival group as high as 66.88 pg/ml (23.48–87.39)." (PMID 37889917, 2023).
COVID-19 (continued). "COVID-19 positive and COVID-19 negative patients had increased levels of IL-1ra, IL-6, IL-8, IL-13, TNF-α, IP-10, MCP-1, MIP-1α, and G-CSF." (PMID 36980378, 2023). "The success rate of IL-6 inhibitors for COVID-19 treatment is only 32%, which does not satisfy the clinical needs." (PMID 36914565, 2023). "The high expression levels of IL-6, TNF-α, and IL-10 may have led to cytokine storms in the neonates of mothers with COVID-19 because the relationship of those cytokines with the event has already been demonstrated in other studies." (PMID 36979888, 2023). "A meta-analysis showed that COVID-19 patients with chemosensory disturbances had lower levels of IL-6 than patients without chemosensory disturbances; other meta-analyses of studies that examined systemic IL-6 levels are consistent with this result." (PMID 37529051, 2023). "The long-COVID-19 group has presented significantly high levels of IL-1β and IL-6 compared to unexposed individuals, but not from recovered COVID-19." (PMID 37018291, 2023). "The Mann-Whitney test showed a significant difference between IL-6 levels in the non-survive and the surviving COVID-19 groups (p 0.00)." (PMID 37889917, 2023). "IL-6, CRP, ferritin, LDH, and D-dimer were increased in all forms of COVID-19." (PMID 37239895, 2023). "This study was conducted using a cross-sectional design by collecting data when COVID-19 sufferers were hospitalised, no further observations were made on the course of the patient’s illness and the results of IL-6 and NLR examinations were not monitored." (PMID 38099004, 2023). "Four studies covering 185 subjects without mild COVID-19 assessed the difference in IL-6 between the MSC and control groups from baseline to about a week." (PMID 37143167, 2023). "Mean levels of CCL1, CXCL10, IL-1ra, IL-6, IL-8 and IL-16 as well as Serpin E1 and C5/C5a are elevated in the CSF of COVID-19 patients compared to non-neurological controls." (PMID 36759861, 2023). "Non-severe COVID-19 cases showed an increase in IL1β, IL-6, IL-10 and TNF and severely ill patients had higher levels of the cytokines IL-6, IL-10 and CXCL8." (PMID 37515295, 2023). "Early in the pandemic, a number of retrospective analyses compared IL-6 levels between patients with COVID-19 ARDS (acute respiratory distress syndrome) compared with non-COVID-19 ARDS or non-COVID-19 sepsis." (PMID 37650680, 2023). "In agreement with published data, we observed that severe COVID-19 increased immune exhaustion, lysosome pathway, and Type III interferon, combined with elevated NF-κB and IL-6 signaling leading to increased levels of circulating pro-inflammatory cytokines, or “cytokine storm”." (PMID 37033961, 2023). "The regulation of the expression of IL-6 and RIG-I, which are two genes essential for the immunological response to COVID-19 infection, could impact the severity of COVID-19 symptoms." (PMID 37759744, 2023). "In COVID-19 ARDS, syndecan-1 increased IL-6, which was significantly higher than in pneumonia." (PMID 36776845, 2023). "Despite the enthusiasm generated at the early stages of the pandemic that COVID-19 is an IL-6-driven disease, it soon became evident that not all severe patients have increased IL-6 at hospital admission." (PMID 37674148, 2023). "Finally, we found that monocytes from convalescent COVID-19 patients produced less TNF-α and IL-6 in response to LPS stimulation, than those from uninfected controls." (PMID 38250080, 2023). "After the second dose of the COVID-19 vaccine, these cytokines also induced TNF-α and IL-6." (PMID 37049424, 2023). "Lung samples from COVID-19 autopsies revealed that the inflamed pulmonary endothelium expressed IL-1β, IL-6, IL-15 and TNF-α, in contrast to non-infected tissue samples, recruiting inflammocytes along the alveolar epithelium." (PMID 37568402, 2023).
COVID-19 (continued). "Cytokine content increased in healthy-pregnant subject-EVs compared to non-pregnant EVs, while IL-2 and IL-6 levels were decreased in COVID-19-pregnant subject-EVs compared to healthy-pregnant subject-EVs (p = 0.043, p = 0.0390, respectively)." (PMID 37560162, 2023). "Regarding COVID-19, eight studies showed increased IL-1β, IL-6, and TNF-α in these cases compared to the controls, five studies showed elevated IL-6 alone, and one study indicated higher TNF-α alone." (PMID 37106750, 2023). "Elevated levels of CRP, ferritin, and IL-6 concentrations have been shown to be higher in cytokine storm disorders, patients with severe COVID-19, and in non-survivors of COVID-19 compared to discharged patients." (PMID 35303909, 2022). "Interleukin 6 (IL6) levels and SARS-CoV-2 viremia have been correlated with COVID-19 severity." (PMID 35783606, 2022). "This decreased expression of certain cytokines (IL-2, IL-6, TNF-α, and IFN-γ) in the nasopharyngeal milieu may be considered early biomarkers for disease severity in COVID-19 patients." (PMID 36584119, 2022). "The results of network pharmacology analysis showed that Yinqiao powder may inhibit inflammatory responses by suppressing IL-6, CXCL2, TNFα, NF-κB, etc., in the treatment of COVID-19." (PMID 36467981, 2022). "In addition to IL-6, CRP at diagnosis showed a good predictive ability of death in CHD patients with COVID-19 (the best cut-off value of 7.4 mg/dL, sensitivity of 87%, and specificity of 94%) (AUC: 0.9306; 95%CI: 0.8175–1.000; p = 0.006)." (PMID 36422198, 2022). "Moreover, by using bioinformatics tools, we found that IL-6 and RIG-I are potential targets for hsa-miR-149-5p as a key player in the immune response against COVID-19." (PMID 36081604, 2022). "During the development of COVID-19, SARS-CoV-2 infection induced an excessive immune response and released a variety of pro-inflammatory cytokines through the JAK/STAT pathway, such as IL-2, IL-6, and granulocyte colony-stimulating factor signaling." (PMID 35721149, 2022). "Besides IL-1β, IL-6, and TNF, several cytokine storm-related factors are potential therapeutic targets for the treatment of severe COVID-19 patients." (PMID 34983527, 2022). "Also, the effect of MAFLD on the progression of COVID-19 is determined by the rate of secretion of proinflammatory mediators such as TNF-α and IL-6." (PMID 36531832, 2022). "Recently, two patients with ARDS mediated by COVID-19 were treated with ex vivo expanded allogeneic Tregs, resulting in symptom improvement, rapid decrease in inflammatory markers (IL-6, IL-12, TNF-α, IFN-γ) and no adverse effects related to the treatment." (PMID 36499448, 2022). "In this study, we identified that the serum levels of IL-6, IL-2R, IL-10, TNF-α, IL-1β, IL-4, IL-8 and IL-17 were significantly elevated in the severe or death cases and probably play crucial roles in the progression of COVID-19." (PMID 35237162, 2022). "Therefore, drugs targeting the IL-6/JAK/STAT axis developed in the past to cope with other diseases (mainly autoimmune diseases), are under analysis for COVID-19 treatment." (PMID 36289890, 2022). "Additionally, multiple signaling pathways (e.g., IL-6/JAK/STAT, NF-kΒ, IFN-Ι), which are prominent in oncogenesis, have been proved to contribute to COVID-19 etiopathogenesis, as well." (PMID 36298472, 2022). "Procalcitonin is elevated in COVID-19 proportional to disease severity and we propose that IL-6 mediates this independent of bacterial coinfection." (PMID 35531376, 2022). "A recent comprehensive meta-analysis reported the enhanced level of Interferon-γ (IFN-γ), TNF-α, IL-10, IL-8, IL-6, IL-4, IL-2R and IL-2, whereas no significant increase in IL-17 and IL-1β level among severe COVID-19 patients." (PMID 36298704, 2022). "Another mechanism that may also be involved in the development of AKI in COVID-19 is the storm of pro-inflammatory cytokines (IFN-γ, IL-6, IL-8 and TNF-α) induced by SARS-CoV-2, which activates nuclear factor kappa B (NF-kB)." (PMID 37675003, 2022).